MEG3 (maternally expressed 3)
Diseases named in the same sentence as MEG3 in open-access papers (continued):
Sharing a sentence is not in itself a finding about the gene and the disease.
tumor (continued). "The tumor-associated proteins identified in study, PDIA6, MEG3, SDCCAG3, IGHG1 and IGHG3 have been previously reported to have cancer-associated properties." (PMID 23977302, 2013). "The correlation between MEG3 downregulation and advanced pathologic stage, tumor size, and patient survival time was also explored." (PMID 24098911, 2013). "Sequence analysis using genomic DNA from 40 primary HCC tumours revealed 16 specimens informative for MEG3 and 24 specimens informative for DLK1 (in total 31 informative cases)." (PMID 23145177, 2012). "The maternally expressed gene 3 (MEG3) was the first lncRNA proposed to function as a tumor suppressor." (PMID 21489289, 2011). "Therefore, future efforts must extend into in vivo models to delineate how MEG3 expression dynamics influence tumor growth, metastatic dissemination, and treatment responsiveness in a physiological setting." (PMID 41480643, 2026). "By positioning MEG3 as a mediator of drug sensitivity, our study not only consolidates its role in tumor biology but also suggests that the efficacy of both nanotechnology-based and conventional therapies is tightly interwoven with the lncRNA regulatory landscape." (PMID 41480643, 2026). "Its functional outcomes align with those of MEG3, making them cooperative in curbing tumor growth." (PMID 40242248, 2025). "Furthermore, preclinical studies have demonstrated that the upregulation of MEG3 significantly inhibits tumor growth in animal models." (PMID 40242248, 2025). "Overall, these data suggest that MEG3 could function as a context-dependent negative regulator in the tumor microenvironment and a biomarker of nodal spread in PTC." (PMID 41154428, 2025). "RNA-based therapeutics, including antisense oligonucleotides (ASOs) and small interfering RNAs (siRNAs), those aimed at modulating MEG3 expression, often encounter issues such as rapid degradation by nucleases, poor cellular uptake, and limited bioavailability at the tumor site." (PMID 40242248, 2025). "Conversely, tumor-suppressor lncRNAs like MEG3 and GAS5 can enhance pro-apoptotic signaling." (PMID 41020820, 2025). "Moreover, upregulation of MEG3 expression increases the sensitization of tumor cells to radiation therapy and chemotherapy, thereby boosting the efficacy of current treatment approaches." (PMID 40242248, 2025). "MEG3 acts as a tumor suppressor by sponging miR-708 that targets SOCS3." (PMID 40002172, 2025). "MEG3, a tumor suppressor lncRNA, is generally downregulated in HBV-associated HCC." (PMID 40625740, 2025). "To identify proteins bound to MEG3 which may mediate MEG3 function in tumor progression, we attempted to purify MEG3 lncRNP assembled in vivo." (PMID 40548301, 2025). "Therefore, further research is essential to optimize these delivery mechanisms, ensuring that therapeutic agents, such as MEG3 effectively reach their intended targets within the tumor microenvironment." (PMID 40242248, 2025). "MEG3 could significantly suppress tumor growth as evidenced in tumor xenograft implantation in nude mice." (PMID 40242248, 2025). "For instance, bringing back the expression of tumor‐suppressive RNAs such as miR‐223 or MEG3 may reduce inflammation that promotes tumors while speeding up the process of autophagy." (PMID 40671967, 2025).
tumor (continued). "As pointed out earlier, the expression of MEG3 is downregulated in multiple cancers; therefore, tumor cells may promote VEGF expression through downregulation of this lncRNA." (PMID 40429961, 2025). "Moreover, the combined expression of miR-124 and MEG3 emerged as an independent prognostic factor in RCC, where the overexpression of miR-124 or MEG3 inhibited cell proliferation, migration, and invasion, and restrained tumor growth." (PMID 40242248, 2025). "Specifically, MEG3 could play a tumor-suppressive role, resulting in a promising therapeutic target for modulating disease pathways involved in ER+/PR+ BC." (PMID 40243758, 2025). "MEG3 is considered as a tumour suppressor in cancers including EC." (PMID 38893244, 2024). "When miR-183 activity was increased, it upregulates BRI3, whose positive relationship correlates with p38/ERK/AKT and Wnt/β-catenin pathways, suggesting a complicated tumor-promoting mechanism which includes interaction among MEG3, miR-183, and BRI3 via p38/ERK/AKT and Wnt/β-catenin signaling." (PMID 38279330, 2024). "In addition, Studies have proved that lncRNAs manipulate early tumor development through different signaling pathways, for example, lncRNA MEG3 can suppress tumor progression by promoting the expression of P5313." (PMID 38778157, 2024). "Interestingly, the proportion of the Mac_MEG3 cluster in tumour samples was found significantly increased, while Mac_FCN1 and Mac_CCL3 clusters were significantly dominant in normal samples." (PMID 39548559, 2024). "Notably, the lncRNA MEG3 antagonizes RAC1 expression in thyroid carcinoma by interacting with its 3’-UTR mRNA to function as a RAC1 tumor inhibitor." (PMID 38745221, 2024). "The maternally expressed gene 3 (MEG3) is a tumor suppressor lncRNA on human chromosome 14q32." (PMID 39108882, 2024). "The different mechanism is that MEG3 may also play an important role in inhibiting tumor proliferation and invasion in addition to DNA damage." (PMID 38827318, 2024). "Serum MEG3 was also strongly correlated with the tumor anatomical site among obese CRC patients." (PMID 38704452, 2024). "MEG3 is a maternally imprinted gene known to have tumour-suppressive properties in various cancers." (PMID 39416175, 2024). "In addition, MEG3 expression was negatively related to local tumor invasion, clinical stage, and lymph node metastasis in NPC." (PMID 39049088, 2024). "The session of MEG3 can suppress cell proliferation and inhibit tumor growth in different cancers." (PMID 39108882, 2024). "Importantly, tumor invasiveness significantly declined in the group expressing high levels of MEG3 compared with the group expressing low levels of MEG3 (p = 0.0014)." (PMID 38827318, 2024). "Restoring MEG3 function in vitro impaired the tumorigenic abilities of GSCs, evidenced by inhibited cell growth, migration, and colony formation, alongside reduced in vivo tumor growth, thereby attenuating infiltration." (PMID 39015773, 2024). "Finally, a tumor cell xenograft mouse model was used to verify the effect of MEG3 on tumor growth and invasiveness." (PMID 38827318, 2024). "MEG3 acts as a tumor suppressor and is downregulated in many human tumors." (PMID 38334963, 2024). "The low expression or absence of MEG3 is associated with large tumor size, advanced FIGO stage, deep infiltration, early metastasis, and low survival rate." (PMID 38281945, 2024). "It has been shown that the expression level of MEG3 is decreased in cancer cells, and up-regulation of MEG3 may inhibit tumor development." (PMID 38472261, 2024). "MEG3 is a tumor-suppressive lncRNA that is downregulated in HCC." (PMID 38334963, 2024). "Meg3 is a tumor suppressor which was reported to be downregulated in LC." (PMID 38245882, 2024). "We suggest that MEG3 negatively correlates with tumor invasion in GHPA." (PMID 38827318, 2024).
tumor (continued). "Recent findings reveal that lncRNA MEG3 functions as a tumor suppressor in different cancer types." (PMID 39553554, 2024). "However, the association of HOTTIP rs1859168 and MEG3 rs7158663 polymorphism with NPC susceptibility and tumor progression remains undetermined." (PMID 39049088, 2024). "For instance, the lncRNA MEG3 level was found to be lower in patients with stage III−IV NFPA than those with stage I−II, with the former displaying a higher invasiveness than the latter, while overexpression of MEG3 inhibited the migration and invasion of PA tumor cells." (PMID 37904679, 2023). "MEG3 can also upregulate tumour suppressors by interacting with regulatory miRNAs." (PMID 37525401, 2023). "Besides GAS5, other lncRNAs have been studied for their tumor-suppressive functions, such as MEG3 and TUG1, reviewed elsewhere." (PMID 37370745, 2023). "First, we accessed the expression of MEG3 in tumor tissues of PCa patients using RT-qPCR." (PMID 38047026, 2023). "In vivo experiments have demonstrated that overexpressed MEG3 can effectively inhibit tumor growth." (PMID 37901333, 2023). "Maternally expressed gene 3 (MEG3), a lncRNA, functions as a tumor suppressor." (PMID 36851033, 2023). "MEG3 is well-known in this respect as a tumor suppressor lncRNA." (PMID 37280524, 2023). "Additionally, mice were injected with PC3 cells transfected with sh-MEG3 and treated with niraparib, and the xenograft tumor growth was observed." (PMID 38047026, 2023). "Therefore, our results proposed that niraparib mitigated PCa tumor growth in vivo through regulating the MEG3/miR-181-5p/GATA6 axis." (PMID 38047026, 2023). "Recently, the mechanism of MEG3 inhibiting tumor progression has attracted extensive attention." (PMID 36468944, 2023). "Another tumor suppressor in PC, MEG3, was also reported to suppress gemcitabine resistance." (PMID 38813489, 2023). "Regarded as a tumor suppressor, previous studies mainly focus on the antitumor effect of MEG3." (PMID 36778210, 2023). "Additionally, niraparib administration restrained tumor growth in a PCa xenograft mouse model, while MEG3 silencing treatment retarded these effects." (PMID 38047026, 2023). "MEG3 is a tumour suppressor that is downregulated in glioma." (PMID 37837401, 2023). "IDH1 mutant tumours showed significant overexpression of MEG3." (PMID 37525401, 2023). "It was clearly observed that tumor volume and weight were conspicuously decreased after niraparib injection compared with injection of PBS, whereas MEG3 silencing could retarded niraparib-mediated tumor inhibition." (PMID 38047026, 2023). "A tumour-suppressive function has also been discovered for MEG3 and TUG1." (PMID 38203731, 2023). "Increasing data support that lncRNA MEG3 acts as a tumor suppressor in cancers including NSCLC." (PMID 37308993, 2023). "Likewise, NOD‐SCID mice transplanted with AML cell lines overexpressing MEG3 had decreased leukemic infiltration to the spleen and increased survival, demonstrating the tumor suppressor activity of MEG3 in AML." (PMID 37267628, 2023). "Additionally, it has been shown that MEG3 inhibits bladder cancer cell progression and tumor growth by promoting PTEN expression through sponging miR-494." (PMID 38047026, 2023). "Additionally, the finding that MEG3's expression is higher in IDH mutant patients than wild‐type patients is consistent with the tumour suppressor role of the MEG3 gene demonstrated in the previous studies." (PMID 37525401, 2023). "Emerging data have shown that lncRNA MEG3 can act as a tumor suppressor by sponging miR-21-5p." (PMID 37308993, 2023).
tumor (continued). "MEG3 is the first lncRNA to be identified as a tumor suppressor." (PMID 36851033, 2023). "MEG3 is significantly downregulated in several human tumors and tumor cells." (PMID 37388937, 2023). "MEG3 can also effectively inhibit tumor growth in nude mice tumor grafts." (PMID 37901333, 2023). "Conversely, the tumor volume, weight and cell necrosis of Hela-CR cells overexpressing MEG3 was significantly reduced after cisplatin treatment compared to those Hela-CR cells without MEG3 overexpressed, and the effect of MEG3 overexpression was reversed by the administration of agomiR-21." (PMID 36344947, 2022). "Exogenous overexpression of MEG3 was reported to lead to tumor cells to regain drug sensitivity, suggesting that MEG3 may regulate the biological activity of tumor cells by modulating their drug sensitivity." (PMID 36344947, 2022). "PDCD4 expression was also found to positively correlate with MEG3 expression in tumour cells." (PMID 35847932, 2022). "Meanwhile, upregulated MEG3 expression could regulate CC proliferative property and induce apoptosis, suggesting that MEG3 has a tumor suppressive effect in CC." (PMID 35979035, 2022). "Since NEAT1 and MIR155HG are oncogenic and MEG3 is tumor-suppressing, the effect of RES on MEG3 may be a predominant contributor to apoptosis of these cells." (PMID 36552560, 2022). "MEG3 is a class of lncRNA, which is considered a tumor suppressor." (PMID 36551518, 2022). "MEG3 has been known as a tumor suppressor, and its downregulation could be found in various cancers." (PMID 36551518, 2022). "Furthermore, upregulation of EZH2 in MEG3‐overexpressing cells decreased the anti‐tumour effect of MEG3." (PMID 35257481, 2022). "Moreover, a group from Jilin University clarified that overexpression of MEG3 inhibited autophagy of tumor cells, thus improving the sensitivity of vincristine." (PMID 36544907, 2022). "For each type of tumor, MEG3 can exert its effects through multiple pathways." (PMID 36544907, 2022). "Previous experiments by our team support anti‐tumour activity of MEG3 in NB." (PMID 35257481, 2022). "Two years later, a research group from Sun Yat-sen University revealed that MEG3 might inhibit tumor growth and metastasis by modulating the miR-21-E-cadherin axis." (PMID 36544907, 2022). "Another research group found that miR-770 and its host gene MEG3 might play a tumor-suppressive role in GC." (PMID 36544907, 2022). "Many studies have demonstrated that MEG3 functions as a tumor suppressor." (PMID 35954272, 2022). "Overall, these data verified that MEG3 acts as a tumor suppressor in choriocarcinoma." (PMID 36544907, 2022). "Meg3 is a maternally expressed imprinted gene that functions as a lncRNA tumor suppressor." (PMID 35664469, 2022). "However, the MEG3 gene expression is lost in many primary human tumors and tumor cell lines due to gene deletion, promoter hypermethylation, and hypermethylation of the intergenic differentially methylated region (J.)." (PMID 35860793, 2022). "Furthermore, we also discuss the clinical importance of MEG3, as well as their potential in tumor prognosis and antitumor therapeutic strategies." (PMID 36551518, 2022). "Finally, animal experiments substantiated the anti-tumor effect of MEG3 and its promotive effect on the sensitivity to chemotherapy." (PMID 35761379, 2022). "MEG3 is a large non-coding RNA (lncRNA) tumor suppressor whose expression is lost in NFPAs." (PMID 35646715, 2022). "Together, these data indicate that MEG3 serves as a tumor suppressor in ESCC." (PMID 36544907, 2022). "MEG3 is the first lncRNA that has been found to have tumor suppressive function." (PMID 34976181, 2022). "Hence, MEG3 can function as a tumor suppressor through increasing E-cadherin, PBLD and RBMS3 by inhibiting miR-421, miR-4513 and miR-141-3p respectively." (PMID 36544907, 2022).
tumor (continued). "MEG3 suppresses tumor growth by inhibiting the Wnt/β-catenin pathway." (PMID 36544907, 2022). "In addition, lncRNA MEG3 has shown biomarker value, prognostic value and therapeutic response measurement in tumor diseases." (PMID 36523500, 2022). "Therefore, we demonstrate that suppression of histone deacetylation and DNA methylation restores epigenetically silenced tumor suppressors such as MEG3, P16, PTEN and STAT1, resulting in inhibition of tumor cell growth." (PMID 35646715, 2022). "In summary, these data suggest that MEG3 is involved in RCC tumor suppression." (PMID 36544907, 2022). "For example, in the prognosis of patients with gastriccardia adenocarcinoma (GCA), miR-770 and its host gene MEG3 may play a tumor suppressor role and hypermethylation in the proximal promoter and enhancer regions." (PMID 35632672, 2022). "In addition, we noted that in tumor samples the expression level of MEG3, TIMP, DAPK1 and SOX1 was lower, while the expression of MLH1 and MALAT1 was higher in comparison to the normal samples." (PMID 35682732, 2022). "In addition, the overexpression of MEG3 inhibited tumor migration and facilitated apoptosis in vivo." (PMID 35898889, 2022). "Interestingly, the tumor suppressor MEG3 promotes tumor progression through targeting miR-4261, modulating the expression of DKK2, β-catenin, Bcl-2, and c-Myc, thus activating the Wnt/β-catenin signaling pathway." (PMID 35448163, 2022). "As previously addressed, MEG3 is considered a tumor-suppressor lncRNA." (PMID 35978835, 2022). "MEG3 also acts as a tumor suppressor through several other mechanisms or pathways." (PMID 36544907, 2022). "In OC cells, MEG3 could inhibit tumor cells migration and invasion potentials by sponging up miR-219a-5p and miR-30e-3p, resulting in the downregulation of EGFR and increase in laminin subunit alpha 4 (LAMA4), respectively." (PMID 36551518, 2022). "However, it has been found that maternally expressed gene 3 (MEG3) is usually deleted in many human tumor cell lines." (PMID 36124026, 2022). "Moreover, a team from Hebei University provided new insights into the molecular pathogenesis of triple-negative BC, where lncRNA MCM 3AP-AS1 promoted tumor cell proliferation by downregulating MEG3." (PMID 36544907, 2022). "Whereas, ectopic expression of MEG3 could inhibit the proliferation, migration, and invasion of tumor cells, and promote tumor cells apoptosis." (PMID 36544907, 2022). "LncRNA MEG3 (MEG3 is an imprinted gene located at 14q32 that encodes a lncRNA, and the decreased MEG3 expression has been reported in multiple cancer tissues) is decreased in HGSOC and is a hallmark for tumor progression in HGSOC." (PMID 35465017, 2022). "Therefore, we calculated the Pearson correlation between MEG3 expression and these cytokines in our tumor samples and found TGFβ3 to be the most significantly associated with MEG3 expression (Pearson’s rho = 0.74)." (PMID 36231143, 2022). "Given this high correlation, we hypothesized that MEG3-expressing tumors may be secreting cytokines that recruit and activate tumor fibroblasts, including members of the TGFβ superfamily and PDGFα/β." (PMID 36231143, 2022). "Moreover, a multidrug resistance-reversing agent, Schisandrin A, has been reported to repress the tumor growth in choriocarcinoma cells by upregulating MEG3 expression and downregulating PI3K/AKT/NF-κB signal cascade." (PMID 34885213, 2021). "The ability of MEG3 to suppress cell proliferation led to its recognition as a tumor suppressor." (PMID 33722609, 2021). "Consistent with its function as a tumor suppressor, MEG3 expression is repressed in several tumors." (PMID 33435206, 2021). "MEG3 upregulated key tumor suppressors mainly by interacting with the regulatory miRNAs." (PMID 34322395, 2021).